IRX3 (iroquois homeobox 3)
Diseases named in the same sentence as IRX3 in open-access papers (continued):
Sharing a sentence is not in itself a finding about the gene and the disease.
Obesity (continued). "Important genes associated with fat and obesity metabolism were located on CHI18 (23 Mb), including the Iroquois Homeobox 3 (IRX3) gene, which acts as a regulator of energy metabolism and is linked to pathways involving the FTO obesity variant mechanism." (PMID 39944650, 2025). "It is found that obesity involves genetic changes involving hypothalamic Iroquois homeobox 3 (Irx3) gene." (PMID 40906133, 2025). "FTO and IRX3, the prioritized genes of habitual snoring, were overrepresented in the FTO-obesity-variant-mechanism gene set (PFDR = 0.0005)." (PMID 38461358, 2024). "Obesity research suggests that the FTO gene region alters the function of nearby genes (IRX3 and IRX5), which impact the involvement of fat cells in thermogenesis." (PMID 38746260, 2024). "In addition, the FTO obesity‐associated polymorphisms were associated with the expression of the homeobox gene Iroquois class homeobox protein 3 (IRX3), and the hypothalamic expression of IRX3 gene is reported to be associated with body composition and calorie intake." (PMID 38556726, 2024). "Recently it was found that FTO can influence IRX3 expression, a protein involved in obesity and the browning of adipose cells resulting that carriers of protective FTO T allele has lower IRX3 expression and lower adipose tissues than AA homozygotes." (PMID 39203789, 2024). "FTO upregulates RPGRIR1L in humans, increasing the lean body mass; furthermore, Iroquois Homeobox 3 (IRX3) which was also upregulated by FTO in human obesity, was found on the same loci in bats." (PMID 39596561, 2024). "We integrate multi-omics and functional information to resolve the colocalizing signals and identify high-confidence effector genes, including FTO and IRX3, which provide proof-of-concept insights into the epidemiologic link between obesity and both diseases." (PMID 37433298, 2023). "Mutated FTO (rs1421085) interacts with Iroquois-class homeodomain proteins IRX-3 and IRX-5, which are also linked to obesity in humans and animals." (PMID 36839421, 2023). "By genetically engineering Irx3 and Irx5 mice, the group showed the presence of an anti-obesity phenotype in Irx3 knockout and Irx5 heterozygous mice." (PMID 35205324, 2022). "IRX3 plays an important role in obesity and type 2 diabetes; however, it plays an important role in the adaptability of tumor cells to metabolic challenges, a process that has a parallelism with the development of chemotherapeutic resistance." (PMID 36338974, 2022). "By contrast, in T/T non-obesity risk (higher thermogenic potential) genotype individuals, the ARID5B repressor binds to this DNA site and thus blocks the expression of IRX3 and IRX5, allowing the formation of the browning adipocytes." (PMID 34895148, 2021). "As obesity-risk variants of FTO affect the expression levels of both IRX3 and IRX5, Irx3/5dHet mice serve as a preclinical model mimicking lower IRX3 and IRX5 expression levels in humans." (PMID 34795556, 2021). "The observed association between an intronic variant in FTO and obesity is explained by the presence of an enhancer within this intron that interacts with the neighbouring IRX3 gene and alters its expression with an impact on obesity." (PMID 34461824, 2021). "Together, our results revealed that hIRX3 overexpression can promote thermogenesis in brown/beige adipose tissue in vivo, and provide a more comprehensive understanding of the role of IRX3 in energy balance and obesity." (PMID 33776928, 2021). "Recent studies further demonstrated that two homeobox genes, IRX3 and IRX5, in the vicinity of FTO directly mediate the effects of obesity-risk variants of FTO on body mass and composition regulation." (PMID 34795556, 2021). "For example, an obesity-associated FTO variant (rs1421085) was found to disrupt an ARID5B repressor motif in an enhancer for IRX3/IRX5 during adipocyte differentiation, increasing obesity risk." (PMID 30617125, 2019).
Obesity (continued). "Two loci associated with ESKD have been previously associated with obesity traits (FTO and IRX3), but our SNVs are low frequency and more common in African ancestry." (PMID 31178898, 2019). "The rs1421085 single-nucleotide variant present in the obesity risk region dictates the extent of local recruitment of ARID5B to the IRX3 enhancer, with consequent regulation of IRX3 expression." (PMID 29346763, 2018). "But surprisingly, subsequent investigations revealed that the obesity-associated, non-coding region within the FTO gene actually serves as an enhancer element for the IRX3 gene through long-range chromatin interactions with its promoter." (PMID 29914202, 2018). "Taken together, we demonstrated that IRX3 played a promoting role in the browning of WAT and its rare variants are associated with human obesity." (PMID 28988979, 2017). "Obesity-associated cis-acting elements in non-coding region of FTO regulate the expression of IRX3 gene, thus activating obesity networks." (PMID 27390851, 2016). "Obesity-associated FTO intron has been reported to contain enhancers and spatially connect with IRX3 in both human and mouse." (PMID 26868054, 2016). "Only a very small number of above-threshold GWAS loci, including SORT1 for LDL cholesterol, the FTO/IRX3 locus for obesity, and the SCN5A/SCN10A locus for QRS duration, have been investigated in detail." (PMID 27162171, 2016). "Recently it has been reported that a long-range interaction between intron 1 of FTO and enhancer of the homeobox gene IRX3 governs IRX3 gene expression, thus influencing cell fate decisions leading to obesity." (PMID 27390851, 2016). "Using the aP2-CRE for adipose-specific IRX3 inhibition, they show that at the organismal level, adipose specific IRX3 knockdown in mice resulted in 57% reduced fat mass ratio and high-fat-diet induced obesity resistance." (PMID 26557137, 2015). "As with Fto, perturbing the expression of these genes in mice results in a bodyweight phenotype, with homozygous deletion of Irx3 resulting in a smaller mouse while heterozygous deletion of Rpgrip1l leading to a mild obesity phenotype." (PMID 25830092, 2015). "An interaction of the obesity-associated intronic region of FTO and the promoter sequence of Iroqouis 3 (IRX3) has recently been identified." (PMID 26431034, 2015). "As it has been proposed that IRX3 and RPGRIP1L are primarily responsible for the enhanced obesity associated with the obesity-related SNPs in FTO12, 13, we compared mRNA levels of FTO, IRX3 and RPGRIP1L in WT gWAT and MEFs." (PMID 25881961, 2015). "Obesity-linked SNPs were associated with IRX3 expression in these samples, but not with expression of FTO, directly linking these variants to IRX3 regulation." (PMID 25265168, 2014). "SNPs (single nucleotide polymorphisms) on a chromosome 16 locus encompassing FTO, as well as IRX3, 5, 6, FTM and FTL are robustly associated with human obesity." (PMID 25242086, 2014). "Recent studies have shown that the obesity‐associated SNPs embedded in the first intron of FTO are influencing expression of different, distant genes, called RPGRIP1L and IRX3, instead of affecting FTO itself." (PMID 25501432, 2014). "More research needs to be conducted to clarify the role of RPGRIP1L and IRX3 in obesity and their relation to FTO." (PMID 25501432, 2014). "This is altered by diet-induced obesity, wherein the levels of IRX3 are less than normal." (PMID 40906133, 2025). "IRX3 gene expression level influences obesity by changing energy consumption and food intake." (PMID 37200795, 2023). "Interestingly, another FTO regulator pathway revealed that the promotion of FTO downregulated the obesity-related gene iroquois homeobox protein 3 (IRX3) level in the hypothalamus and macrophage." (PMID 36157445, 2022).
Obesity (continued). "For example, SNPs associated with obesity and type-2 diabetes that are located in noncoding regions of the FTO gene locus interact with the promoter of the IRX3 gene at megabase distances, thus affecting the expression of IRX3, which regulates body weight in mice." (PMID 35465097, 2022). "Iroquois-related homeobox 3 is considered to be a determinant for obesity, in relation to the fat mass and obesity associated (FTO) genes, due to the role of Irx3 in neurogenesis at the paraventricular nucleus of the hypothalamus, developed from the anterior hypothalamus." (PMID 35546872, 2022). "The IRX3 relationship with obesity and the process of browning in adipose cells has been described." (PMID 35627568, 2022). "This mice study also found that Irx3 is a functional long-range target of obesity-associated variants within the FTO gene, and both Irx3 and FTO interact, increasing body fat deposition and leading to obesity among animals." (PMID 35498742, 2022). "Interestingly, Speakman indicated that FTO gene polymorphisms mediate their obesity effects via nearby genes such as RPGRIP1L and IRX3." (PMID 34399781, 2021). "Besides their developmental functions, IRX3 and IRX5 have been highlighted as determinants of human obesity in connection with the intronic obesity risk variants of FTO, a gene in the vicinity of the IRXB cluster." (PMID 34795556, 2021). "However, in the same study, mice homozygous for a new deletion mutation of Irx5 (Irx5Δ/Δ) exhibited early postnatal lethality, whereas heterozygous Irx5Δ/+ mutant mice were found to show an anti-obesity phenotype like Irx3 knockout mice." (PMID 34795556, 2021). "The Iroquois homeobox 3 (IRX3) gene was recently reported to be a functional downstream target of a common polymorphism in the FTO gene, which encodes an obesity-associated protein; however, the role of IRX3 in energy expenditure remains unclear." (PMID 33776928, 2021). "Iroquois homeobox 3 gene (IRX3) is a human obesity-related gene that has recently been identified." (PMID 32192102, 2020). "Another super-enhancer, which is located on an obesity-risk associated locus of the intronic region of the FTO gene, was linked to the regulation of browning in subcutaneous fat by determining the level of IRX3 and IRX5." (PMID 32316277, 2020). "The elucidation of IRX3 function stems from research on human obesity." (PMID 32192102, 2020). "Experiments have shown that T>C base changes in rs1421085, an intronic variant of the FTO gene found in GWASs on obesity, is involved in the regulation of adipocyte thermogenesis by increasing the expressions of nearby IRX3 and IRX5, but not FTO." (PMID 32271837, 2020). "The rs9939609 is in linkage disequilibrium with rs1421085 (T>C), which may lead to obesity through the disruption of AR1D5B- mediated repression of Irx3 and Irx5." (PMID 31622411, 2019). "Recent studies reported that the partial inhibition of hypothalamic IRX3 exacerbates obesity." (PMID 31126299, 2019). "Consistently, IRX3-deficient mice are leaner and do not develop obesity after being place on a high fat diet, and hypothalamus-specific dominant-negative IRX3 mice also present with the same phenotype as IRX3-deficient mice." (PMID 31482095, 2019). "It has also been reported that Irx3 knockout mice were protected against obesity." (PMID 31126299, 2019). "Because GWAS SNPs and their target genes may not always exhibit highly significant correlation in eQTL analysis, exemplified by obesity SNP rs9930506 and IRX3 gene, we set the significance threshold as nominal P-value < 0.05." (PMID 30972099, 2019). "The use of 3C allowed for the discovery of a new role for IRX3, as it had never before been associated with obesity." (PMID 29741584, 2018).
Obesity (continued). "Although recent studies suggested that FTO has an effect on BMI, at least partly, through the change in the expression levels of other obesity-related genes such as IRX3, Moreover, a complete LD was found in the present study between three neighboring SNPs of the first intron region of the FTO gene." (PMID 29677190, 2018). "Moreover, IRX3 knockout mice had body weights approximately 30% less than their wild-type littermates, suggesting that the IRX3 gene is closely related to obesity." (PMID 29736189, 2018). "In human brain samples tested, these obesity-related variants showed an association with expression levels of IRX3, but surprisingly not with FTO as previously predicted." (PMID 29741584, 2018). "Thus, our findings provided an intact picture of IRX3's function in browning program and human obesity." (PMID 28988979, 2017). "We also found significantly lower expression of IRX3 in the subcutaneous fat of obese subjects, which was consistent with two previous studies, further supporting the involvement of IRX3 in human obesity." (PMID 28988979, 2017). "A recent report revealed that SNPs in FTO could influence obesity by altering the expression of the adjacent genes IRX3 and RPGRIP1L." (PMID 28208657, 2017). "Although those 15 obesity-associated SNPs are located within the first intron of FTO, it should be noted that some of the variants can form long-range functional connections with the homeobox gene IRX3, which is a half-megabase downstream of the variants." (PMID 29126384, 2017). "This raises the possibility that the effects of FTO genotype on fetal growth and postnatal obesity may have originated through IRX3 expression in embryonic life." (PMID 26907388, 2016). "However, IRX3 expression was even lower in isolated adipocytes of obese compared to lean children and correlated with obesity-related measures of adipocyte hypertrophy and inflammation." (PMID 27560134, 2016). "Concluding from the observed association of IRX3 expression with FTO obesity risk variants and UCP1 expression in adipocytes of lean children, one may expect increased IRX3 expression in obese subjects." (PMID 27560134, 2016). "Obesity associated SNPs in FTO were found to be associated with the expression of IRX3, but not FTO, in the cerebellum of the human brain." (PMID 26907388, 2016). "Within this study, we aimed to assess whether the link between the FTO risk genotype and IRX3 and IRX5 expression in AT is related to the development of obesity and to alterations of AT biology in children." (PMID 27560134, 2016). "Indeed, IRX3 expression in adipocytes negatively correlated with obesity-related parameters of AT dysfunction, i.e. adipocyte diameter and AT inflammation as indicated by the number of infiltrating macrophages and CD68 mRNA expression in the SVF." (PMID 27560134, 2016). "Mouse models of increased IRX3 and IRX5 expression as well as in vivo models harboring the human mutations are necessary to fully understand the association between FTO intron 1 and obesity." (PMID 26557137, 2015). "Thus, further studies are necessary to answer the question if either FTO or IRX3, or both are “the” obesity gene(s)." (PMID 26431034, 2015). "Overall, these animal experiments suggest that the genes IRX3 and RPGRIPL1 may mediate at least in part the association of SNPs in FTO with obesity." (PMID 25825681, 2015). "Expression QTL studies in human brains revealed that obesity associated SNPs in FTO are associated with expression of IRX3, but not FTO itself." (PMID 25825681, 2015). "An obesity-associated SNP in intron 1 of FTO has been associated with decreased browning of white adipose tissue, which coincided with an increase in expression of IRX3 and IRX5 in preadipocytes." (PMID 26788058, 2015). "Indeed, recent data focussing on obesity associated variants within FTO have implicated two neighbouring genes, RPGRIP1L and IRX3, as having a functional link between the SNP and the observed human phenotypes." (PMID 25830092, 2015).
Obesity (continued). "The interaction of the FTO gene SNPs with the Iroquois homeobox 3 (IRX3) and Iroquois homeobox 5 (IRX5), genes also associated with the development of obesity and an effector of the FTO variants, may jointly regulate adipogenesis and cause white adipose tissue browning in mice." (PMID 37200795, 2023). "While the exact mechanism remains to be unraveled, it has been shown that genetic variants within the FTO gene are linked functionally to another obesity-related gene called IRX3, which promotes browning of white adipocytes, maybe a connecting link between FTO variants and obesity-related disorders." (PMID 32346024, 2020). "Moreover, obesity-associated SNPs correlated with IRX3 expression in the human brain, but not with that of FTO—suggesting that the association signal overlaps an enhancer element involved in long-range regulation of IRX3 in the brain." (PMID 32603637, 2020). "Polymorphisms in the intron regions of FTO gene may act as a regulator of other genes such as Iroquois homeobox 3 (IRX3) and obesity-associated single nucleotide polymorphisms of FTO were associated with expression of IRX3, but not FTO, in human brains." (PMID 32843047, 2020). "Variants in this gene have previously been shown to associate with birthweight and the development of obesity and diabetes Their functional impact may be in modifying expression of the IRX3 and IRX5 genes, rather than FTO itself." (PMID 31616461, 2019). "Besides SIM1 and MC4R, the haploinsufficiency of proprotein convertase 1 (PCSK1), melanocortin 2 receptor accessory protein 2 (MRAP2) in the brain, iroquois homeobox 3 (IRX3) in fat or uncoupling protein 3 (UCP3) in mitochondria are also responsible for human obesity." (PMID 31124015, 2019). "Some recent studies have suggested that the association between FTO SNPs in intron 1 and obesity might be owing to their potential influence on expression of IRX3, IRX5, and RPGRIP1L, rather than on their expression of FTO." (PMID 30105001, 2018). "Taken together, these findings may suggest that IRX3 plays a crucial regulatory role in the browning program possibly based on the specific genetic background, and genetic-based stratification may be needed to determine the effectivity of anti-obesity intervention by targeting IRX3." (PMID 28988979, 2017). "Finding IRX3 mRNA and protein expression decreased in adipocytes of obese children, we further evaluated whether IRX3 expression may also be related to obesity related AT alterations." (PMID 27560134, 2016). "Importantly, a disease-associated SNP may not necessarily influence the nearest gene, as is the case for obesity-associated SNPs within the FTO gene, which appear to influence the expression of a more distal gene, IRX3." (PMID 27935966, 2016). "Another group reported that obesity variants within the FTO gene formed a long-range connection with IRX3, which was located downstream from FTO, and deficiency in this gene resulted in 25–30% body weight loss, thus questioning a direct role for FTO in obesity." (PMID 27249342, 2016). "The potential functional link between FTO and IRX3 is supported by evidence from murine, human, and in vitro studies showing that the IRX3 promoter strongly interacts with the obesity-associated interval within FTO, and that obesity-linked SNPs are associated with IRX3 but not with FTO expression." (PMID 27560134, 2016). "While it remains controversial as to whether the obesity-related SNPs in FTO act via modulation of FTO function or by influencing adjacent genes such as IRX3 and RPGRIP1L, our results provide firm evidence that FTO modulates adipogenesis, and thereby fat mass, both in vitro and in vivo." (PMID 25881961, 2015). "Furthermore, long-range functional connections were observed between enhancers within the obesity-associated Fto interval and Irx3 expression (and not Fto) in adult mouse brain tissues." (PMID 26788058, 2015).